PALB2 (partner and localizer of BRCA2)
Diseases named in the same sentence as PALB2 in open-access papers (continued):
Sharing a sentence is not in itself a finding about the gene and the disease.
Familial adenomatous polyposis (3 papers, 2019 to 2025). Familial adenomatous polyposis (FAP) is characterized by the development of hundreds to thousands of adenomas in the rectum and colon during the second decade of life. "As expected, MUTYH associated with recessive familial adenomatous polyposis, the only two homozygotes of which also carry biallelic MUTYH variants, had the highest allele frequency, followed by VHL, BRCA1, BRCA2, and PALB2." (PMID 39301547, 2024).
leukemia (3 papers, 2012 to 2021). A malignant (clonal) hematologic disorder, involving hematopoietic stem cells and characterized by the presence of primitive or atypical myeloid or lymphoid cells in the bone marrow and the blood. "The distinct clinical phenotype of D1 and N patients (severely affected, often combined with leukemia or solid tumors below the age of 5 years) may provide a clue to favor BRCA2/FANCD1 and PALB2/FANCN as the first gene to be screened." (PMID 22778927, 2012).
lymph node metastasis (3 papers, 2018 to 2021). "Interestingly, higher expression of PALB2 was significantly associated with poorer overall survival (P < 0.01) in patients with stage III or nearby lymph node metastasis (N1, N2 or N3)." (PMID 29321957, 2018).
ovarian tumors (3 papers, 2013 to 2022). "Beyond these mutations, germline or somatic aberrations in genes of the homologous recombination (HR) pathway such as RAD51B/C/D, PALB2, ATM, BRIP1 may confer an HR deficiency in up to 50% of ovarian tumors." (PMID 36531003, 2022).
peritoneal carcinoma (3 papers, 2017 to 2023). A peritoneum cancer that is located in the inside of the abdomen. "Primary peritoneal carcinoma has also been reported in a patient with PALB2 mutation following RRBSO." (PMID 35159349, 2022). "PALB2 germline truncating variants were observed in 0.2–0.6% of women diagnosed with ovarian, fallopian tube and peritoneal carcinoma." (PMID 28858227, 2017). "Additionally, both preneoplastic FTE lesions and primary peritoneal carcinoma have been reported in PALB2 heterozygote patients." (PMID 35159349, 2022).
prostate tumors (3 papers, 2022 to 2024). "We propose that future studies should explore this RAD18/UBC13/PALB2/RNF168 fork recovery pathway in additional models of BRCA1-deficient cancers, including breast and prostate tumors." (PMID 38943334, 2024). "We employed 14 patient-derived tumor graft models pancreatic, lung, and prostate tumor graft models harboring HR mutations (BRCA1/2, CHK1/2, ATM/ATR, PALB2, PARP1/2, RAD51, FANCA/B) to compare LP-184’s potency with PARPi olaparib." (PMID 38630886, 2024). "We next examined mutational signatures of HR deficiency in PALB2- and BARD1-mutant prostate tumors." (PMID 35768576, 2022).
sarcoma (3 papers, 2021 to 2025). A usually aggressive malignant neoplasm of the soft tissue or bone. "However, PALB2 variant has been observed in the patient treated due to sarcoma who also carried the variants within PALB2 and MITF genes." (PMID 40040726, 2025). "The role of PALB2 variants in the pathogenesis of sarcomas has not been proved." (PMID 40040726, 2025).
serous carcinoma (3 papers, 2013 to 2022). "A few months later, a 55 years-old woman diagnosed with ovarian high-grade serous carcinoma tested negative for BRCA1/2 and PALB2 in a broad HBOC clinical panel (Ref.11 for the panel), however the same truncating variant c.1516G > T;p.E506* in MRE11A was identified." (PMID 33510186, 2021).
uterine cancer (3 papers, 2017 to 2021). Primary or metastatic malignant neoplasm involving the uterine corpus and/or the cervix. "We found that PD-L1 in tumours (breast, stomach, colorectal and uterine cancers) with BRCA2, PALB2 or Ku70/80 mutations showed higher expression than in tumours without such mutations." (PMID 29170499, 2017).
anemia (2 papers, 2022 to 2026). A reduction in the number of red blood cells, the amount of hemoglobin, and/or the volume of packed red blood cells. "Several BRCA1/2 interactors, such as PALB2 (FANCN), RAD51 (FANCR), and BRIP1 (FANCJ), are also Fanconi anemia proteins." (PMID 40841483, 2026). "BRCA1 and 2 interacts with a number of other DNA repair proteins to form a complex system for DNA damage repair, including ATM, RAD51, PALB2, MRE11A, RAD50, NBN, and the Fanconi anemia proteins." (PMID 35785170, 2022).
bipolar disorder (2 papers, 2014 to 2021). A disorder of the brain that causes unusual shifts in mood, energy, activity levels and the ability to carry out day-to-day tasks. "According to GWAS (Genome Wide Association Study) catalog, PALB2 gene has been seen associatedwith bipolar disorder." (PMID 34092963, 2021). "SNP rs420256 in PALB2 has been reported to be associated with bipolar disorder in Caucasians in previous studies." (PMID 25390645, 2014).
cervical cancer (2 papers, 2024 to 2025). A primary or metastatic malignant neoplasm involving the cervix. "Expression of the DNA repair enzymes BRCA1/2, PALB2, and RAD51 were increased in cancer samples compared to controls, indicating that double-stranded DNA repair activity increases during cervical cancer progression." (PMID 39672307, 2024). "Expression of PALB2 was increased in HPV16-positive precancers as compared to HPV31-positive precancers, further supporting its role in cervical cancer progression." (PMID 39672307, 2024).
cholangiocarcinoma (2 papers, 2024). A carcinoma that arises from the intrahepatic biliary tree (intrahepatic cholangiocarcinoma) or from the junction, or adjacent to the junction, of the right and left hepatic ducts (hilar cholangiocarcinoma). "Consistent with loss of function of PALB2, this cholangiocarcinoma was characterized by strong mutational signatures of HRD." (PMID 39406235, 2024).
chordoma (2 papers, 2022 to 2024). Chordomas are rare malignant tumors arising from embryonic remnants of the notochord in axial skeleton. "Our study is the first to show that PALB2 expression is associated with chordoma recurrence, besides, we established a nomogram comprising PALB2 and clinical features for predicting the PFS of chordoma." (PMID 36158641, 2022). "While few PALB2 mutations or copy number variation was found in whole-genome sequencing in chordoma." (PMID 36158641, 2022). "One such study performed germline whole-exome sequencing in 19 familial chordoma patients and reported defects in PALB2 and BRCA2 in 17 patients, the PALB2 mutation co-segregated with disease in one family." (PMID 38700789, 2024). "Cell counting kit-8, colony formation, transwell migration, and invasion assays were used to assess the proliferation, migration, and invasion of chordoma cells with PALB2 knockdown." (PMID 36158641, 2022). "In summary, our results reveal that high PALB2 expression indicates a poor prognosis of chordoma patients and promotes the malignant phenotypes of chordoma cells in vitro." (PMID 36158641, 2022). "The expression of PALB2 in 187 human chordoma tissues was analyzed by immunohistochemical staining, and we found that PALB2 was variedly expressed between chordoma patients, with the H-scores range from 1.74 to 177.5." (PMID 36158641, 2022). "In conclusion, our results reveal that high PALB2 expression indicates a poor prognosis of chordoma patients and promotes the malignant phenotype of chordoma cells in vitro." (PMID 36158641, 2022). "The proliferation of chordoma cells significantly reduced at 72 hours and 96 hours after si-PALB2 transfection compared to the si-NC group." (PMID 36158641, 2022). "The proliferation, migration, and invasion of chordoma cells significantly decreased after PALB2 knockdown." (PMID 36158641, 2022). "This study aimed to study the role of PALB2 on the prognosis of skull base chordoma patients and the proliferation, migration, and invasion of chordoma cells." (PMID 36158641, 2022). "Univariate Cox(All the variables satisfy the PH assumption) revealed that high PALB2, partial resection, conventional chordoma, large tumor volume, the rich blood supply of the tumor, and high Al-mefty classification were risk factors for PFS." (PMID 36158641, 2022). "Given the high resistance of chordomas to chemotherapy, PALB2 may aid in identifying potential chemotherapy-sensitive chordomas, and further studies are highly needed." (PMID 36158641, 2022). "Interestingly, we found that there were more conventional chordomas in the high PALB2 group (P=0.02)." (PMID 36158641, 2022). "As for the possible downstream mechanisms of PALB2 in chordomas, we hypothesize that PALB2 may influence cell cycle and autophagy based on our analysis in other tumors." (PMID 36158641, 2022). "The effect of PALB2 in chordoma cells was assessed in both UM-Chor1 and MUG-Chor1." (PMID 36158641, 2022). "Moreover, we explored the effect of PALB2 on chordoma cells using several cellular experiments in vitro." (PMID 36158641, 2022). "Our study is the first to propose high PALB2 indicates an adverse prognosis in chordoma." (PMID 36158641, 2022). "However, our study found that high PALB2 expression patients had an adverse prognosis, and knockdown PALB2 inhibited the proliferation, migration, and invasion of chordoma cells." (PMID 36158641, 2022). "In addition, We perform KEGG enrichment analysis for genes significantly correlated (cor>0.3, P<0.05) with PALB2 in chordoma." (PMID 36158641, 2022). "High PALB2 expression indicated an adverse prognosis in chordoma." (PMID 36158641, 2022). "Thus, the observed differences in PALB2 expression levels in chordoma might be due to the regulation of transcription and translation." (PMID 36158641, 2022). "However, to date, the role of PALB2 in chordoma remains to be studied." (PMID 36158641, 2022). "This suggested that PALB2 may function through different mechanisms in chordomas." (PMID 36158641, 2022).
chordoma (continued). "However, few PALB2 mutations were found in large chordoma genome sequencing, suggesting that the role of PALB2 mutations reported in other tumors may not be applicable in chordomas." (PMID 36158641, 2022). "However, the effect of PALB2 on the prognosis of chordomas has not been previously reported." (PMID 36158641, 2022).
Ewing sarcoma (2 papers, 2023 to 2025). A small round cell tumor that lacks morphologic, immunohistochemical, and electron microscopic evidence of neuroectodermal differentiation. "We present the case of a pediatric patient who developed Hodgkin lymphoma at the age of 8 years and secondary Ewing sarcoma at the age of 16 years with a positive family history of cancer, who carries a germline heterozygous variant of unknown significance in the PALB2 gene." (PMID 40040726, 2025).
Infertility (2 papers, 2019 to 2025). "Several CDK2-bound genes have also been implicated in other aspects of germ cell development, including Palb2, Pds5b, Safb1, and Herc4, or have been investigated as potential markers of infertility in human populations: Mtrr and Vdac3." (PMID 31350280, 2019).
lung adenocarcinoma (2 papers, 2022 to 2023). A carcinoma that arises from the lung and is characterized by the presence of malignant glandular epithelial cells. "In lung adenocarcinoma, USP22, adeubiquitinase highly overexpressed in multiple cancer types, has been shown tomodulate PALB2 levels through its C-terminal WD40 domain to promotechemoresistance." (PMID 35293552, 2022).
stomach adenocarcinoma (2 papers, 2018 to 2021). "Of the individuals with sporadic stomach adenocarcinoma and PALB2 mutations from the TCGA database, we selected 88 individuals with diffuse gastric cancer, as described by Bass and colleagues, among which we did not identify any truncating PALB2 variants." (PMID 29706558, 2018).
acute leukemia (1 paper, 2024). A clonal (malignant) hematopoietic disorder with an acute onset, affecting the bone marrow and the peripheral blood.
apocrine sweat gland cancer (1 paper, 2021). A malignant neoplasm involving the apocrine sweat gland. "In the current study, we identify a metastatic cutaneous apocrine sweat gland cancer with a biallelic PALB2 mutation." (PMID 34084283, 2021).
B-cell non-Hodgkin lymphoma (1 paper, 2016). The most common type of non-Hodgkin lymphoma. "A particularly important aspect of the clinical phenotype of the patients with a PALB2 defect described in this study is that both affected individuals developed B cell non-Hodgkin lymphoma (B-NHL)." (PMID 26990772, 2016).
cardiomyopathy (1 paper, 2022). A disease of the heart muscle or myocardium proper. "This yield increased to 3.41% with the expanded ACMG SF v3.0 list, identifying an additional 71 individuals, most of whom are protein-truncating variant carriers in the newly included cardiomyopathy gene TTN (53/71) and hereditary breast and ovarian cancer (HBOC) syndrome gene PALB2 (11/71)." (PMID 36335097, 2022).
Ductal Carcinoma (1 paper, 2025). "Quantitative analysis of confocal microscopy images revealed distinct patterns of IQGAP1 and PALB2 expression across the two different ductal breast carcinomas after probing with anti-IQGAP1 antibody and anti-C-terminus PALB2 Ab; both cases reported in this study lack the BRCA2-interacting domain." (PMID 40868059, 2025).
endometrial tumor (1 paper, 2021). "Tumor mutational signatures provided evidence that germline variation in BRCA1, PALB2, RAD51C, MUTYH and NTHL1 can be (but is not always) associated with tumor mutational signatures consistent with a functional role of these genes in endometrial tumor development." (PMID 33917078, 2021).
ependymoma (1 paper, 2023). A WHO grade II, slow growing tumor of children and young adults, usually located intraventricularly. "High expression of CXorf67, a DNA damage response protein that competes with BRCA2 for PALB2 interaction to impair the HR pathway, could increase sensitivity to PARP inhibitors in PFA ependymomas." (PMID 36793373, 2023).
germ cell tumor (1 paper, 2023). A benign or malignant, gonadal or extragonadal neoplasm that originates from germ cells. "Germline truncating mutations of PALB2 (c.3350+5G>A, splice region) and BARD1 (p.Q206fs) were detected in immature teratomas (classified as germ cell tumors), which showed particularly high HRD scores." (PMID 35676859, 2023).
Gynecomastia (1 paper, 2020). Abnormal development of large mammary glands in males resulting in breast enlargement. "ATM, BRCA1, PALB2, RAD51B, and XRCC3 promoter methylation levels were evaluated in paired tumor, normal tissue, and adjacent lymph nodes, and in gynecomastia tissue samples." (PMID 32295201, 2020). "Among the five gene promoters tested, only two - RAD51B and XRCC3—disclosed statistically significant differences between tumor and gynecomastia tissue samples, whereas ATM, BRCA1, and PALB2 did not." (PMID 32295201, 2020).
hepatoblastoma (1 paper, 2017). Hepatoblastoma (HB) is a malignant hepatic tumor and is the most common pediatric liver cancer. "The development of hepatoblastoma in this BWS infant can be explained by predisposition of UPD at 11p15.5 as well as possibly of APC and PALB2 mutations and later by somatic events with CTNNB1 somatic mutation and 1q gain acting as driver alterations." (PMID 29190888, 2017). "Although the APC and PALB2 germline mutations were not predicted as being pathogenic, further studies are necessary to conclude whether these two mutations play a synergistic role for the tumorigenesis of hepatoblastoma." (PMID 29190888, 2017).
in situ carcinoma (1 paper, 2024). A malignant epithelial neoplasm which is confined to the epithelial layer without evidence of further tissue invasion. "For patients with in situ carcinoma, the BRCA1/2 double mutation frequency was 0.10% (2/2079), and the BRCA1/2 and PALB2 triple mutation frequency was 0.05% (1/2079)." (PMID 38439896, 2024).
intrahepatic cholangiocarcinoma (1 paper, 2025). A carcinoma that arises from the intrahepatic bile duct epithelium in any site of the intrahepatic biliary tree. "We presented a case of a patient with advanced intrahepatic cholangiocarcinoma (iCCA) harboring dual somatic homologous recombination repair (HRR) gene pathogenic variants, specifically BRCA1 and PALB2, who achieved PR lasting approximately 7 months following salvage treatment with olaparib." (PMID 40822464, 2025).
kidney cancer (1 paper, 2021). Primary or metastatic malignant neoplasm involving the kidney. "The PALB2 mutations (509_510delGA) were present in one (0.1%) of 810 cases with kidney cancer and in seven (0.15%) of 4702 controls (OR = 0.8; 95% CI, 0.10–6.75; p = 0.86)." (PMID 33419454, 2021). "The patient with kidney cancer and mutation in 172_175delTTGT died 3 years after kidney cancer of diagnosis but the patient with mutation in second investigated variant of gene PALB2 was still alive until March 2020." (PMID 33419454, 2021). "The 810 kidney cancer cases and 4702 controls were successfully genotyped for the two PALB2 variants." (PMID 33419454, 2021). "Among 810 unselected kidney cancer cases two PALB2 mutations were reported in two patients (0,24%) (odds ratio [OR], (OR = 1.2; 95% CI 0.25–5.13; p = 0.84)." (PMID 33419454, 2021). "Our main goal was to determine the prevalence of PALB2 (509_510delGA and 172_175delTTGT) mutations in bladder and kidney cancer patients from Polish population." (PMID 33419454, 2021). "We were interested to investigated if mutations in PALB2 genes could be relevant to the pathogenesis of bladder or kidney cancer." (PMID 33419454, 2021). "In 30 family cases with kidney cancer in first- and/or second-degree relatives we did not observed any of investigated mutations in gene PALB2." (PMID 33419454, 2021). "The mutations in PALB2 gene seem not to play a major role in bladder and kidney cancer development in Polish patients." (PMID 33419454, 2021). "In this study we did not do multivariable analysis because the presence of a PALB2 (509_510delGA and 172_175delTTGT) mutations were not statistical significant among bladder and kidney cancer patients." (PMID 33419454, 2021). "The results of our unselected cohort 1413 bladder, 810 kidney cancer cases and 4702 controls revealed no statistical significant, indicating that two mutations of PALB2 gene (509_510delGA and 172_175delTTGT) do not seem to play a major role in bladder or kidney cancer development." (PMID 33419454, 2021).
Klinefelter syndrome (1 paper, 2024). A sex chromosome disorder caused by the presence of an extra X chromosome in the male karyotype. "Mutations in genes such as BRCA2 and PALB2 have been identified as contributors, with some cases associated with Klinefelter syndrome, emphasizing the diverse genetic landscape." (PMID 39512981, 2024).
larynx cancer (1 paper, 2021). A primary or metastatic malignant neoplasm involving the larynx. "Interestingly, we identified a patient with double heterozygous PALB2 c.857delC and BRCA1 c.3286C>T mutations who was diagnosed with bilateral breast, ovarian, and larynx cancers." (PMID 34439348, 2021).
lung squamous cell carcinoma (1 paper, 2024). "However, the Lung-MAP SWOG S1400G trial (NCT02154490) found that talazoparib (Talzenna) had a lower ORR of 4% in patients with advanced refractory lung squamous cell carcinoma, specifically in tumors with BRCA1/2, ATM, ATR, and PALB2 mutations." (PMID 38989152, 2024).